ST3GAL4 (ST3 beta-galactoside alpha-2,3-sialyltransferase 4)
Diseases named in the same sentence as ST3GAL4 in open-access papers (continued):
Sharing a sentence is not in itself a finding about the gene and the disease.
tumor (continued). "Altered sialylation by enzymes like ST3GAL4 and ST6GALNAC1 can contribute to tumor immune evasion and metastasis and is an emerging therapeutic strategy." (PMID 40018643, 2025). "We found that FAM207A interacts with CD4+ memory T cells and ST3GAL4, and their activation was negatively correlated with FAM207A expression (R = –0.28), indicating that FAM207A is a potential tumor biomolecular target." (PMID 35102149, 2022). "Similar results were obtained with patient-derived primary-tumor samples; while overexpression of ST3Gal3/6 was detected in one MYCN-amplified patient sample (NB1), overexpression of ST3Gal4 was found in the other (NB2)." (PMID 30344930, 2018).
infection (17 papers, 2011 to 2025). The state of being infected such as from the introduction of a foreign agent such as serum, vaccine, antigenic substance or organism. "For both LCMV and LASV, sialylation of the lysosomal host factor at a specific N-linked glycosylated residue by ST3GAL4 is required for infection, N104 in the case of CD164 and LCMV and N76 in the case of LAMP1 and LASV." (PMID 35235462, 2022). "Similarly, at day 7 PI, infection caused a significant decrease of St3Gal4, while St6GalNAc1, St6Gal1, and St3Gal1 showed a trend toward reduction." (PMID 39412866, 2024). "In contrast, WU95Hu−H3 infection of ST3Gal4-transfected cells was relatively low in comparison to binding but relatively efficient in ST6Gal1-transfected cells." (PMID 40487452, 2025). "In accordance, infection levels similar or even higher as observed in HEKWT or HEKN cells were obtained in HEKΔSiaN cells transfected with ST3Gal4 or ST6Gal1." (PMID 40487452, 2025). "Receptor binding specificity was compared to receptor-specific infection efficiency by plotting, for both, the 2-3Sia/2-6Sia ratio derived from ST3Gal4-and ST6Gal1-transfected HEKΔSiaN, HEKΔSiaO, HEKΔSiaGSL, and HEKΔSia cells." (PMID 40487452, 2025). "Compared to control cells, all KO cell lines (ST3GAL4, SLC31A1, ST6GAL1, and ST3GAL4/ST6GAL1DKO) showed significantly reduced PEDV infection." (PMID 40767522, 2025). "KO of ST3GAL4 inhibited PEDV infection, indicating that ST3GAL4 is essential for efficient infection by PEDV." (PMID 40767522, 2025). "Here, as for N-glycans, sialylation of type II LN on O-glycans or GSLs by ST3Gal4 efficiently supported infection of HU02Av−H5 and, somewhat less, HK68Hu−H3." (PMID 40487452, 2025). "At day 7 PI, expression of St6GalNAc1 increased significantly upon infection, while St3Gal4 expression decreased." (PMID 39412866, 2024). "An ST3Gal4 concentration-dependent increase of infection by 2-6Sia specific strains BK79 and WU95 was observed in combination with the highest concentration of ST6Gal1 (0.8 ng)." (PMID 35831293, 2022). "The highest expression level of STs in human respiratory tissues are ST6GAL1 and ST3GAL4, which are closely related to the infection of influenza viruses (41, –, 43)." (PMID 35044216, 2022). "Collectively, these data directly demonstrate a role of CD164, SLC35A1, and ST3GAL4 in LCMV-GP–mediated infection at the entry step and validate their importance for infection with WT LCMV." (PMID 35235462, 2022). "The ST3GAL4-KO-2 cell line was determined to possess the best antiviral effect by measuring the virus titer and cell survival rate at 36 h after infection with the Sw/HuB/H1N1 strain, so it was selected for the following work." (PMID 34200006, 2021). "Sialyltransferase St3gal4 also demonstrated a significant upregulation in transcription in the lungs 7 days after infection." (PMID 27335862, 2013). "Comparison of infection into transiently transfected HEKΔSia cells with stable knock-ins of ST6Gal1 or ST3Gal4 in HEKΔSia cells validated the use of the cell-based glycan array as specificity and efficiency of infection by strains WU95Hu−H3 and HU02Av−H5 was similar in both cases." (PMID 40487452, 2025). "Here, we compared virus binding to ST3Gal4- or ST6Gal1-transfected cells with infection." (PMID 40487452, 2025). "However, expression of all sialyltransferase-encoding genes was mostly downregulated by RVC and both RVA viruses with the exception of ST3Gal4 and the major Sialyl-Tn synthase—ST6GalNAc1 whose expression was marginally upregulated after infection with both RVA strains." (PMID 37848925, 2023). "Compared to WT cells, infection of these viruses was significantly reduced in cells lacking ST3GAL4 and ST6GAL1." (PMID 40767522, 2025). "Using a LCMV-pseudotyped virus and an infection period of 3 weeks, the authors identified seven host factors important for LCMV entry, four of which (CD164, ST3GAL4, SLC35A1, and MAN1A2) were contained within the set of 37 factors identified in our live virus screen." (PMID 35502904, 2022).
infection (continued). "Infection of A549 cells with a recombinant LCMV-Armstrong engineered to express GFP, LCMV-2A-GFP, also show a marked reduction in infection upon inactivation of CD164, ST3GAL4, or SLC35A1." (PMID 35235462, 2022). "Similarly, an ST6Gal1 concentration-dependent increase of infection by 2-3Sia specific strains HU02 and PR8 was observed in combination with the highest concentration of ST3Gal4 (0.2 ng)." (PMID 35831293, 2022). "Several sulfotransferases and a sialyltransferase were also tested, but only HS3ST1 and ST3GAL4 were detected in the abomasum and their transcription level did not change during infection." (PMID 21569362, 2011). "Remarkably, infection of cells by WU95Hu−H3 was not increased upon transfection with ST3Gal4 even though WU95Hu−H3 and FU02Hu−H3 displayed similar 2-3Sia/2-6Sia KD ratios and infection of FU02Hu−H3 was increased by ST3Gal4 transfection of all four cell lines." (PMID 40487452, 2025).
ST3GAL4 also shares sentences with these, for which no sentence is quoted: breast carcinoma (7 papers); depression (3); atherosclerosis (2); cervix squamous cell carcinoma (2); hepatocellular carcinoma (2); leukemia (2); pancreatic adenocarcinoma (2); autoimmune disease (1); benign meningioma (1); bladder cancers (1); bladder tumors (1); brain cancer (1); cardiovascular disease (1); chronic lung disease (1); Cirrhosis (1); congenital disorder of glycosylation (1); coronary artery calcification (1); demyelinating disorders (1); epilepsy (1); foot and mouth disease (1); head and neck squamous cell carcinoma (1); Hypercholesterolemia (1); Hypertension (1); liver cancer (1); lung adenocarcinoma (1); lymph node metastasis (1); malignant meningioma (1); membranous nephropathy (1); mucinous neoplasm (1); multiple myeloma (1).
A further 7 diseases each share a sentence with ST3GAL4 in 1 paper.